DIO3OS (DIO3 opposite strand upstream RNA)
Synonyms: NCRNA00041; DIO3-AS1; C14orf134; DIO3-OS
Gene: Long non-coding RNA gene on chromosome 14 (101,552,221 to 101,620,355, reverse strand). Ensembl gene ENSG00000258498.
Diseases named in the same sentence as DIO3OS in open-access papers:
DIO3OS is named in the same sentence as 31 diseases in open-access papers, as found by Europe PMC text mining. Sharing a sentence is not in itself a finding about the gene and the disease. The quoted sentences say what the papers report.
breast carcinoma (4 papers, 2022 to 2025). "The research showed Dio3os expression upregulation and enhanced aerobic glycolysis in long-term estrogen-deprived, drug-resistant breast cancer cells, underscoring the role of Dio3os in regulating cancer glycolysis." (PMID 41235096, 2025). "Recent studies have identified decreased Dio3os expression in hepatocellular carcinoma, thyroid carcinoma, and non-small cell lung cancer but abnormally increased in breast cancer and pancreatic cancer." (PMID 41235096, 2025). "This study identified 11 key methylation-driven lncRNAs (DIO3OS, ELOVL2-AS1, MIAT, LINC00536, C9orf163, AC105398.1, LINC02178, MILIP, HID1-AS1, KCNH1-IT1, and TMEM220-AS1) closely associated with breast cancer prognosis through three machine learning methods." (PMID 39456830, 2024). "Collectively, these data indicated that DIO3OS is highly expressed in AI-resistant tumors and clinically relevant to breast cancer resistance to AI treatment." (PMID 36418319, 2022). "Together, DIO3OS positively regulates the estrogen-independent breast cancer cell proliferation and glucose metabolism in vivo." (PMID 36418319, 2022). "Furthermore, Dio3os interacts with polypyrimidine tract binding protein 1 (PTBP1) to facilitate a metabolic shift towards glycolysis in breast cancer cells, thereby promoting increased expression of lactate dehydrogenase A (LDHA)." (PMID 41235096, 2025). "Dio3os, another imprinted gene, is involved in the progression of several cancers, including hepatocellular carcinoma, non-small cell lung cancer, thyroid cancer, pancreatic cancer, and breast cancer." (PMID 41235096, 2025). "Both cell counting and MTT assays revealed that with DIO3OS knockdown by LNAs, the growth of BT549 cells was slightly impaired, while SKBR3 cells remained largely unaffected, indicating a less important role of DIO3OS in these ER-negative or HER2-positive breast cancer." (PMID 36418319, 2022). "Consequently, targeting DIO3OS to restore the sensitivity of breast cancer cells to AI treatment may represent a novel therapeutic approach to overcome AI resistance in ER+ breast cancer patients." (PMID 40303296, 2025). "As the expression of DIO3OS increases in breast cancer cells undergoing AI resistance, the aberrant activation of DIO3OS/PTBP1/LDHA glycolysis cascade may endow tumor cells with metabolic adaptation that allows them to survive from AI-caused estrogen deficiency." (PMID 36418319, 2022). "Here, we demonstrate that lncRNA DIO3OS directly interacts with PTBP1 protein in the nucleus and further stabilizes the mRNA of LDHA by protecting the integrity of its 3’UTR, ultimately activates glycolytic metabolism in AI-resistant breast cancer cells." (PMID 36418319, 2022). "Therefore, DIO3OS specifically interacts with nuclear PTBP1, a splicing regulator that supports the growth and aerobic glycolysis of LTED breast cancer cells." (PMID 36418319, 2022). "Collectively, lncRNA DIO3OS directly interacts with PTBP1 protein in the nucleus and stabilizes the mRNA of LDHA by protecting the integrity of its 3’UTR, which consequently upregulates LDHA expression and activates glycolytic metabolism in AI-resistant breast cancer cells." (PMID 36418319, 2022). "To further explore whether DIO3OS regulates ER-positive breast cancer development in vivo, we orthotopically injected parental MCF-7 cells with or without DIO3OS overexpression in ovariectomized nude mice." (PMID 36418319, 2022).
hepatocellular carcinoma (4 papers, 2019 to 2025). A malignant tumor that arises from hepatocytes. "Conversely, DIO3OS levels were lower in hepatocellular carcinoma tissues, and upregulation of DIO3OS repressed malignant biological behavior by sponging miR-328." (PMID 34504807, 2021). "This study reveals a crucial role of the conserved lncRNA, DIO3OS, in inhibiting the progression of hepatocellular carcinoma (HCC)." (PMID 37271897, 2023).
inflammatory bowel disease (3 papers, 2019 to 2025). A spectrum of small and large bowel inflammatory diseases of unknown etiology. "Repression of Dio3os has been linked to increased cell proliferation, and its repression is a biomarker for inflammatory bowel disease." (PMID 33761883, 2021). "Dysregulation of lncRNA DIO3OS was closely related with inflammatory bowel disease." (PMID 31001325, 2019). "Co-occurrence analysis of the literature was conducted using inflammatory bowel disease, diabetes mellitus, core gene (MMP3), five predicted lncRNAs (TMED10P, NCRNA00092, DIO3OS, CYP2B7P1, CDKN2BAS), and the significantly enriched PPAR pathway as search terms." (PMID 38173213, 2025).
ovarian carcinoma (3 papers, 2017 to 2023). A malignant neoplasm originating from the surface ovarian epithelium. "The lncRNA DIO3OS has been implicated in the development and progression of various tumors; however, its specific role in the development and progression of ovarian cancer has not been investigated." (PMID 35910206, 2022). "Reannotation of microarray probe sets showed that DIO3OS, DNM3OS, MIAT, and MEG3 lncRNA were detected in the two ovarian cancer subtypes at levels similar to known protein coding EMT-linked genes." (PMID 29150601, 2017).
thyroid cancer (3 papers, 2018 to 2025). "Knocking down DIO3OS within thyroid carcinoma cells suppressed cancer cell viability, cell invasion, and migration via regulation of the let-7d/NF-κB2 axis." (PMID 34504807, 2021). "However, an article in 2020 suggested that Dio3os is elevated in thyroid cancer and, as an oncogenic factor in thyroid cancer, may regulate the expression of Nf-KYB2 through the Dio3o/Lt-7d axis, thereby affecting cell viability, DNA synthesis, infiltration, and migration of thyroid cancer cells." (PMID 41235096, 2025).
Obesity (2 papers, 2021 to 2025). Accumulation of substantial excess body fat. "To uncover the roles of Dio3os inactivation in mediating MO female offspring energy expenditure and obesity, we further injected AAV-Dio3os-CMV into MO female offspring interscapular BAT to recover Dio3os expression." (PMID 34824246, 2021). "Here the authors report that Dio3os is an imprinted long-coding RNA that modulates brown adipose tissue development and obesity resistance in the offspring." (PMID 34824246, 2021). "Dio3os activation in BAT also provides a therapeutic target for manipulating BAT thermogenic activity to prevent obesity." (PMID 34824246, 2021). "Considering the crucial role of miR-122 in regulating hepatic cholesterol and fatty acid metabolism, its interaction with Dio3os may influence lipid metabolism and obesity." (PMID 41235096, 2025). "Dio3os activation in BAT prevents MO female offspring from high-fat diet (HFD)-induced obesity." (PMID 34824246, 2021). "Recent research highlighted Dio3os expression suppression in the Brown Adipose Tissue (BAT) of offspring from obese mothers, which affects BAT development and contributes to obesity across generations." (PMID 41235096, 2025). "Consistently, recovering Dio3os expression in MO female offspring profoundly increases BAT thermogenesis, preventing offspring from HFD-induced obesity and metabolic dysfunctions at ambient temperatures." (PMID 34824246, 2021).
anemia (1 paper, 2024). A reduction in the number of red blood cells, the amount of hemoglobin, and/or the volume of packed red blood cells. "Genetic variants in the DIO3OS gene, associated with intracellular thyroid hormone regulation, were found to increase the risk of anemia." (PMID 39749022, 2024).
bladder cancer (1 paper, 2022). "Analysis of TCGA database data by Ualcan revealed that DIO3OS was significantly underexpressed in bladder cancer (p = 1.949 × 10−5), while SNHG1 was significantly overexpressed in bladder cancer (p = 3.889 × 10−11)." (PMID 36230661, 2022). "It was found that only DIO3OS and SNHG1 were significantly differential lncRNAs in bladder cancer." (PMID 36230661, 2022).
breast tumor (1 paper, 2022). "In this work, we compare lncRNA expression profiles in the clinical samples of AI-treated ER-positive breast cancer patients and identify DIO3OS as an important RNA regulator in reprograming glucose metabolism in AI-resistant breast tumors." (PMID 36418319, 2022).
Crohn disease (1 paper, 2021). A gastrointestinal disorder characterized by chronic inflammation involving all layers of the intestinal wall, noncaseating granulomas affecting the intestinal wall and regional lymph nodes, and transmural fibrosis. "Other studies have also shown that the expression levels of DIO3OS were significantly lower in patients with Crohn’s disease and ulcerative colitis than those in healthy controls." (PMID 34504807, 2021).
lipomatous neoplasms (1 paper, 2023). "These outcomes of the TCGA-SARC cohort indicated that the DIO3OS expression was an excellent diagnostic biomarker for distinguishing osteosarcoma from lipomatous neoplasms, myomatous neoplasms, nerve sheath tumors, and synovial-like neoplasms." (PMID 37752544, 2023). "These outcomes suggested that the expression levels of DIO3OS in osteosarcoma were lower than lipomatous neoplasms (p < 0.001), myomatous neoplasms (p < 0.01), and synovial-like neoplasms (p < 0.001)." (PMID 37752544, 2023).
lung adenocarcinoma (1 paper, 2023). A carcinoma that arises from the lung and is characterized by the presence of malignant glandular epithelial cells. "We validated the expression of DIO3OS in driver gene‐negative lung adenocarcinoma patients by FISH experiments, and the results showed that DIO3OS was mainly expressed in the nucleus and partially expressed in the cytoplasm." (PMID 36221911, 2023).
myocarditis (1 paper, 2021). Myocarditis is a condition that is characterized by inflammation of the heart muscle (myocardium). "LncRNA ENSMUST00000222401, termed DIO3OS, was commonly upregulated in four mouse myocarditis models." (PMID 34504807, 2021). "This study suggested that lncRNA DIO3OS is related to inflammation, but the role of DIO3OS in myocarditis requires further study." (PMID 34504807, 2021).
neuroblastoma (1 paper, 2025). Neuroblastoma (NB) is the most common solid, extracranial childhood tumor. "A particular subset of human cell lines displayed co-expression of D3 and Dio3os, while a distinct set of human neuroblastoma cell lines showed co-expression of D3, Dio3os, and Dlk1." (PMID 41235096, 2025).
osteosarcoma (1 paper, 2023). A usually aggressive malignant bone-forming mesenchymal neoplasm, predominantly affecting adolescents and young adults. "Here, for the first time, high expression of DIO3OS was associated with poor prognosis of osteosarcoma and can be a potential diagnostic biomarker to distinguish osteosarcoma from other variety subtypes of sarcoma reported." (PMID 37752544, 2023). "High expression of DIO3OS was identified as a risk lincRNA for predicting overall survival of osteosarcoma in test cohort." (PMID 37752544, 2023). "Based on KM survival analysis results, DIO3OS is a risk lincRNA for predicting the overall survival of osteosarcoma in the TARGET database and GSE39055." (PMID 37752544, 2023). "Based on these results, high expression of DIO3OS was a potential risk factor for poor prognosis in patients with osteosarcoma." (PMID 37752544, 2023). "In conclusion, our outcomes indicated that DIO3OS is a potential diagnostic and prognostic biomarker of osteosarcoma, emphasizing its potential as a target of immunotherapy to improve the treatment of osteosarcoma through TGF-β signaling pathway." (PMID 37752544, 2023). "The aim of this study was to determine the underlying potential mechanisms and function of DIO3OS, a lincRNA in osteosarcoma and clarify that DIO3OS can be used as a potential diagnostic biomarker and immunotherapeutic target." (PMID 37752544, 2023). "This research indicated DIO3OS as a potential diagnostic and prognostic biomarker of osteosarcoma, emphasizing its potential as a target of immunotherapy to improve the treatment of osteosarcoma." (PMID 37752544, 2023). "It was further verified that the expression level of DIO3OS was a reliable diagnostic and prognostic biomarker for patients with osteosarcoma." (PMID 37752544, 2023). "Based on the TARGET database and GSE39055, the results indicated that the DIO3OS expression was up-regulated in osteosarcoma tissues and high expression of DIO3OS was significantly associated with poor prognosis for patients with osteosarcoma." (PMID 37752544, 2023). "In addition, these outcomes of diagnosis and prognosis analysis in the validation cohort further indicated that expression levels of DIO3OS were an excellent diagnostic and prognostic biomarker for osteosarcoma." (PMID 37752544, 2023). "Based on KM survival analysis, the result suggested that osteosarcoma patients with high expression of DIO3OS have a poor overall survival prognosis." (PMID 37752544, 2023). "These outcomes of the present study indicated that inhibiting the expression of DIO3OS sed the ability of metastasis, migration, and invasion of osteosarcoma cell lines and animal models as a novel regulator of TFG-β signaling pathway." (PMID 37752544, 2023). "The results showed that the phosphorylation of SMAD2 was downregulated in osteosarcoma cells transfected with si-DIO3OS and the total SMAD2 expression remained unchanged." (PMID 37752544, 2023). "The expression of DIO3OS up-regulated in osteosarcoma was validated between osteoblast and osteosarcoma in GSE12865 and further indicated between hFOB 1.19 cell line and osteosarcoma cell lines." (PMID 37752544, 2023). "Based on the results of bioinformatics analysis and experiments in vitro, the silencing of DIO3OS plays a crucial role in inhibiting osteosarcoma metastasis." (PMID 37752544, 2023). "This co-expression analysis and KM analysis outcomes further indicated the inhibition of osteosarcoma migration and invasion by silencing DIO3OS expression, possibly through inhibiting the TGF-β signaling pathway." (PMID 37752544, 2023). "As our results showed that DIO3OS is highly expressed in osteosarcoma cell lines and tissues compared to controls, these results indicated that DIO3OS can be used as a diagnostic biomarker for osteosarcoma." (PMID 37752544, 2023). "Then, downregulated DIO3OS expression significantly inhibited the phosphorylation of SMAD2 in osteosarcoma cell lines." (PMID 37752544, 2023).
osteosarcoma (continued). "Therefore, the inhibition of osteosarcoma migration and invasion by silencing DIO3OS expression, possibly through inhibiting the TGF-β signaling pathway." (PMID 37752544, 2023). "Finally, we should further elucidate that the mechanism of DIO3OS accurately regulates the activity of the TFG-β signaling pathway for osteosarcoma metastasis and immune infiltration." (PMID 37752544, 2023). "The results demonstrated that DIO3OS was significantly enriched in the nuclear fraction, revealing that DIO3OS could involve in the development of osteosarcoma in the nuclear fraction." (PMID 37752544, 2023). "The outcome revealed that DIO3OS expression was up-regulated in osteosarcoma." (PMID 37752544, 2023). "Furthermore, after the combined use of DIO3OS silencing and TGF-β signaling pathway activator (TGF-β1), the results revealed that acting the TGF-β signaling pathway restored the affection of DIO3OS silencing on inhibiting the metastasis, migration, and invasion of osteosarcoma in vivo and in vitro." (PMID 37752544, 2023). "Therefore, silencing DIO3OS expression may improve the efficacy of osteosarcoma immunotherapy by inhibiting immune checkpoints (CD200 and TNFRSF25)." (PMID 37752544, 2023). "Therefore, knockout DIO3OS may be a novel immunotherapy for patients with osteosarcoma by inhibiting immune checkpoints (CD200 and TNFRSF25)." (PMID 37752544, 2023). "In addition, DIO3OS may be a novel immunotherapeutic target for osteosarcoma by suppressing immune checkpoints (CD200 and TNFRSF25) and is a novel diagnostic biomarker to distinguish osteosarcoma from multiple other subtypes of sarcoma." (PMID 37752544, 2023). "Therefore, DIO3OS may be a novel potential therapeutic target for osteosarcoma." (PMID 37752544, 2023). "The expression levels of DIO3OS in the metastatic group were higher than those in the non-metastatic group, and patients with osteosarcoma in the metastatic group have a poor overall survival prognosis." (PMID 37752544, 2023).
prostate carcinoma (1 paper, 2016). A carcinoma that arises from epithelial cells of the prostate gland. "In prostate cancer, six lncRNA (LINC00341, RP11-291L15.2.1, DIO3OS, RP11-65F13.2.1, WDFY3-AS2 and RP11-629G13.1.1) cooperatively regulated TGFB which is critical for the development of tumor." (PMID 27580177, 2016).
cancer (9 papers, 2019 to 2025). A tumor composed of atypical neoplastic, often pleomorphic cells that invade other tissues. "Occasionally, the expression levels of DIO3OS are associated with patient survival in several cancers." (PMID 37271897, 2023). "While the involvement of Dio3os in cancer is well-documented, its role in glycolipid metabolism is less understood." (PMID 41235096, 2025). "DIO3OS is generally downregulated across cancers, suggesting its potential tumor‐repressing function in multiple tumors." (PMID 37271897, 2023). "In summary, the conserved lncRNA DIO3OS is broadly downregulated in cancers and strongly represses HCC stemness." (PMID 37271897, 2023). "First of all, to clarify the expression of DIO3OS in other cancer, DIO3OS expression in pan-cancer were evaluated." (PMID 37752544, 2023). "In the present study, it is found that DIO3OS is a conserved lncRNA that is generally downregulated in multiple cancers, including HCC, and its low expression correlates with poor clinical outcomes in HCC." (PMID 37271897, 2023). "Here, we identified a conserved lncRNA, DIO3OS, that is downregulated in almost all cancers, including HCC." (PMID 37271897, 2023). "DIO3OS is specifically involved in the immune system, and its expression is differential in several cancer types." (PMID 37958675, 2023). "DIO3OS was highly overexpressed in a variety of cancer types (including PC) as compared to the corresponding normal tissues." (PMID 31384177, 2019). "In addition, we performed pan‐cancer analysis against key m6AlncRNAs and found that DIO3OS has the potential to be a therapeutic target for a variety of cancers." (PMID 36221911, 2023). "SDHAP1, ZDHHC8P1, and DIO3OS were significantly differentially expressed in several cancer types." (PMID 36221911, 2023). "DIO3OS as a key lncRNA was found to affect tumor cell stemness in a variety of cancers." (PMID 36221911, 2023). "Given that DIO3OS is highly conserved and is generally downregulated in cancers, it may have potential antitumor functions, particularly in HCC." (PMID 37271897, 2023). "Interestingly, we found that DIO3OS was generally downregulated in cancers." (PMID 37271897, 2023). "In in vitro cancer cell lines and an in vivo spontaneous HCC mouse model, DIO3OS markedly represses tumor development via its suppressive role in CSCs through downregulation of zinc finger E‐box binding homeobox 1 (ZEB1)." (PMID 37271897, 2023). "Inhibiting DIO3OS expression by blocking the DIO3OS/let-7d/NF-B2 axis, which lowers the expression of ki-67 and PCNA and reduces cancer cell viability." (PMID 37470034, 2023).